IL4 (interleukin 4)
Diseases named in the same sentence as IL4 in open-access papers (continued):
Sharing a sentence is not in itself a finding about the gene and the disease.
Allergy (705 papers, 2002 to 2026). An allergy is an immune response or reaction to substances that are usually not harmful. "This Th2-cell-like reprograming of Treg cells, that in allergy-susceptible mice is driven by IL-4 production by ILC2s and activated mast cells, supports the interpretation that there is a generally dysfunctional Treg cell response in allergic patients." (PMID 40574856, 2025). "Elevated levels of IL-4 and IL-9 suggest a Th2 profile of the inflammatory response associated with allergy and IL-13 response." (PMID 41239983, 2025). "Natural products inhibit the production of inflammatory factors such as IL-4, IL-5, and IL-13, thereby reducing the inflammatory response caused by allergies." (PMID 41001345, 2025). "IL4R rs1801275 AA, IL13 rs20541 GG, and IL-4 rs2243250 CC genotypes synergistically amplified allergy risk under vitamin D deficiency (adjusted OR = 26.14, p = 0.019; OR = 6.51, p = 0.025; OR = 4.13, p = 0.007)." (PMID 40927566, 2025). "Elevated levels of IL‐4 and IL‐13 are often associated with allergic reactions and are observed in children with AH accompanied by AR." (PMID 38572767, 2025). "Despite its important role in type 2 immune responses, dysregulated IL-4 is implicated in the pathogenesis of allergic diseases, which affect large parts of the global population." (PMID 40561016, 2025). "The production of allergen-specific IgE antibodies, the hallmark of allergic diseases, is completely dependent on the Th2 cytokine, IL-4." (PMID 40725026, 2025). "IL‐4 is associated with allergic responses, particularly in promoting IgE production, a key antibody in allergic reactions." (PMID 41185941, 2025). "In fact, the predisposition of Th17 cells to upregulate IL-4 and become Th2 cells has been associated with the exacerbation of allergic diseases." (PMID 40574856, 2025). "IFN-γ and IL-4 dysregulation is linked to a range of immunological disorders, including infections, autoimmune, and allergy problems." (PMID 38794167, 2024). "Th2 cells respond to antigens from the breast, which in turn triggers IgE production and activation of allergy‐associated immune cells, which in turn are able to promote a pro‐inflammatory cytokine cascade, producing IL‐4 and IL‐5." (PMID 39619969, 2024). "Th2 cytokines, such as IL-4, IL-5 and IL-13, have a number of effects associated with allergy, including IgE class-switching by B cells, eosinophil activation and recruitment, and mucus production." (PMID 40115160, 2024). "In allergic diseases, as well as in IgG4-RD, T helper type 2 (Th2) cells play an important role associated with interleukin 4 (IL-4) and 13 (IL-13) production (Th2 cytokines)." (PMID 39364411, 2024). "We were unable to demonstrate an association of IL-4 rs2243250 and IL-4R rs1801275 with airway allergic diseases in our population." (PMID 39202464, 2024). "Dysregulated IL-4 expression or function has been implicated in various immunological disorders, such as allergic diseases, immunodeficiency, and autoimmune diseases." (PMID 38397895, 2024). "The roles of IL-4 and IL-13 in facilitating the isotype switching of antibodies to IgE point towards their association with allergic reactions." (PMID 38097754, 2023). "The previous investigations have shown the essential oil immunostimulatory effects on T cells and meaningfully inhibited allergy-associated cytokines IL-4 and IL-13." (PMID 36518853, 2022). "The IL-13 gene is located on the 5q31 chromosome, which also encodes other factors involved in allergy mechanisms such as IgE, IL-4, IL-3, and IL-5." (PMID 35629280, 2022). "The application of HDM causes an increase in serum IgE and IL-4 production in rodent allergy models." (PMID 36077570, 2022). "Recently, several studies have found that polymorphisms in the IL-13 and IL-4 genes are often associated with an increased risk of allergic diseases, including atopic dermatitis, allergic rhinitis, and bronchial asthma." (PMID 35629280, 2022).
Allergy (continued). "The IL-4 and IL-13 cytokines produce IgE through increased secretion and action of B cells, which differentiates Th2 cells and causes allergic reactions." (PMID 35889810, 2022). "On the one hand, IL-25 activates type 2 immunity via the relevant cytokines, including IL-4, IL-5, and IL-13, which are associated with the development of pathogenic infection-related allergic diseases." (PMID 36119076, 2022). "On the other hand, BATF/IRF4 complexes bound to IL-4 CNS2 have been implicated in IL-4 transcription in Tfh cells involved in allergic reactions in mouse." (PMID 35812386, 2022). "Th2 response up-regulates the expression of IL-4, IL-5, and IL-13, which are essential for allergic diseases caused by the pathogenic infection." (PMID 36119076, 2022). "IL-4, the main cytokine associated with IgE-mediated allergic reactions, decreased in the Gt-EE group." (PMID 36235405, 2022). "Many similarities exist between IgG4-RD and allergic diseases, such as the increase of eosinophil counts, IgE, IgG4, and Th2 associated cytokines (IL-4, IL-5, and IL-13)." (PMID 35432312, 2022). "Expression of allergy-associated cytokine genes, including Il4, Il5, Il9, Il13, and Il21, was higher in Nr4a-TKO cells, even when compared with Foxp3-KO cells." (PMID 33665581, 2021). "In particular, overexpression of IL-4 has been previously found to be associated with the onset of allergies, which is an inflammatory condition found to be more common in ASD." (PMID 33642989, 2021). "The current study was aimed to study the association of IgE and different variants of Interleukin-4 (IL-4), and Interleukin-13 (IL-13) genes with different kind of allergies." (PMID 34814942, 2021). "IL-4, the marker cytokine of T-helper-2 (Th2) cells plays an important role in allergy-associated inflammatory responses, as it particularly stimulates mast cells and other effector cells to proliferate." (PMID 34572574, 2021). "The hallmark of clinical allergy is the development of allergen-reactive T helper 2 (Th2) cells, which produce Type 2 cytokines (IL-4, IL-5, IL-13) that promote Ig isotype switch in B cells." (PMID 34305927, 2021). "Our study suggests that increased IgE levels and in association with variant forms of IL-4 and IL-13 genes are significantly associated with different types of allergies in study population." (PMID 34814942, 2021). "Th1 lymphocytes produce Interferon-gamma (IFN-γ) while Th2 cells are mainly producers of interleukin 4 (IL-4), IL-5 and IL-13, which is a hallmark of atopy or allergy." (PMID 34063174, 2021). "We therefore investigated the role of IL-4 in respiratory infection and allergy caused by early life Chlamydia infection." (PMID 34226412, 2021). "Both the IL-4 and IL-13 pathways play roles in the inflammation associated with allergies; however, they also play fundamental roles in cellular function." (PMID 34948449, 2021). "This is the first demonstration of the implication of susceptibility genes to allergy in the development of KC, and this is the first time that the IL4 and FOXP3 genes association was analyzed with KC risk in an Algerian population." (PMID 34840678, 2021). "Not only degranulation of MCs but also the control of pathogenic Th2 responses mediated by elevated IL-4 production by these MCs was important for allergy treatment." (PMID 33299086, 2021). "IL-4 forces B cells to produce IgE, and after sensitization and activation of mast cells and basophils, causes initiation of allergic reaction and release of allergic mediators." (PMID 33884360, 2021). "Antigen-specific Th2 cells cause allergic diseases, such as asthma, rhinitis, and atopic dermatitis, by producing Th2 cytokines (IL-4, IL-5, and IL-13)." (PMID 33662037, 2021). "At present, a prior study has demonstrated a close association of IL-4 and its receptor gene polymorphisms with the pathogenesis of allergic diseases." (PMID 33834211, 2021).
Allergy (continued). "Several studies have reported that polymorphisms of IL-4 and/or IL-4R genes are associated with allergic diseases, diabetes, cancers, and pregnancy disorders." (PMID 33920608, 2021). "Th2 cells primarily secrete interleukin-4 (IL-4), IL-5, and IL-13 that participate in a plenty of pathogenic phenomena, such as allergic reaction, hypersensitivity, and IgE and IgG class switching." (PMID 34539675, 2021). "Similar to allergies, helminth infections induce a Th2 immune response associated with cytokines such as interleukin (IL)-4, IL-5, IL-9, IL-13, and increased levels of eosinophils, basophils, mast cells and circulating IgE Abs." (PMID 32268573, 2020). "IL-4 was associated with IgE production and allergy, and we found that the level of IL-4 increased among uncontrolled asthmatics in contrast to controlled asthmatic patients; however, this was statistically insignificant." (PMID 32143340, 2020). "IL‐4 stimulates B‐cells to produce antibodies, and Th2 activation against autoantigen will cause Type1 IgE‐mediated allergy and hypersensitivity, which, in turn, induces vascular hyperpermeability." (PMID 30690926, 2019). "Type 2 cytokines such as IL-4, IL-5, and IL-13 cause airway hyperresponsiveness, mucus secretion, and eosinophil aggregation and induce B lymphocyte to produce IgE-mediated allergic reaction." (PMID 31737687, 2019). "We observed that IL-4, a key Th2-secreted cytokine that mediates lymphocyte differentiation and orchestrates allergic diseases, was significantly associated with better prognosis." (PMID 31069161, 2019). "Excessive secretion of IL-4 by Th2 is associated with increased IgE levels and subsequent allergic reactions." (PMID 30791382, 2019). "We aimed to study the expression of the Th2 cytokine (IL-4, IL-5, and IL-13) genes, which are implicated in allergic reactions, and changes in the actual secretion of the cytokines." (PMID 29772010, 2018). "The cytokine IL-4 is understood to be key to the development of type 2 immune responses that underlie allergic disease pathologies and immunity to parasites; however, the specific role IL-4 plays in CD4 T cell differentiation is less clear." (PMID 29910811, 2018). "The design of the synthetic mammalian cell-based dual TH2 cytokine sensor (DCS) device is based on a common IL-13 receptor (IL-13R) that is shared by the allergy-associated cytokines IL-4 and IL-13." (PMID 29062109, 2017). "Chitin can strengthen the immune system as shown with mice by inducing an accumulation in the tissue of IL-4 expressing innate immune cells (including eosinophils and basophils) associated with allergies." (PMID 28173820, 2017). "The protein-coding genes listed were closely linked to allergy and associated with lncRNAs; moreover, some of them such as Il4, Il5, and Il13 were regulated by iPSC-MSC treatment, and therefore these lncRNAs were also associated with iPSC-MSC immunomodulation." (PMID 28057064, 2017). "The prevention of allergy is known to be associated with the downregulations of IL‐4, IL‐5, IL‐13 and IL‐10." (PMID 28165193, 2017). "Repeated topical application of allergens or haptens causes significant increases in blood IgE and IL-4 levels in a rodent allergy model." (PMID 26825274, 2016). "SNPs and haplotypes in genes encoding IL-4, IL-4R, and IL-13 have been shown to play a critical role in allergy and IgE production." (PMID 27566584, 2016). "Inhibiting IL-4 has been associated with alleviating allergies while the neutralization of IL-10 has been linked to the reduction of helminth infection by restoring the function of Th2 effector cells." (PMID 25705127, 2015). "Since IL-4 has been implicated in the pathogenesis of allergic diseases, IL-4 expression in Tfh cells contributes to their pro-allergic function." (PMID 26278622, 2015). "Th2 cells secrete IL-4 to activate B cells for IgE production, thus inducing activation of mast cells and causing the allergic reaction." (PMID 25861366, 2015).
Allergy (continued). "The levels of pro-inflammatory cytokines (IL-1β, IL-6, TNF), anti-inflammatory cytokine (IL-10), Th2-type cytokines associated with allergy (IL-4, IL-13, IL-33) and Th1-type cytokine (IFN-γ) were analysed from the treated skin sites of all groups." (PMID 25123235, 2014). "It is well recognized that allergic diseases are closely associated with an enhanced Th2 immune response with high levels of IL-4, IL-5, and IL-13, but accumulating evidence also implicates down-regulated Th1 immune responses in the pathogenesis of allergy." (PMID 25090641, 2014). "We investigated the anti-allergic activity of streptochlorin by monitoring the production of allergy-associated cytokines, such as IL-4, INF-γ, and TNF-α, in the ear lobes after DNFB treatment." (PMID 24086321, 2013). "The T allele of a promoter single nucleotide polymorphism of the interleukin-4 gene, C-589T (also known as C-590T or rs2243250), has been associated with a higher level of serum IgE and a higher risk of allergy." (PMID 23383309, 2013). "In adipose tissue, eosinophil that migrates from the blood into adipose tissue, can produce IL-4 and IL-13, cytokines typically associated with the arm of the immune system that causes allergy but also protect against infection with parasites." (PMID 23894289, 2013). "Animals fed high doses of chicken OVA secrete more interleukin-4 (IL-4; associated with allergy) and less TGF-β (associated with tolerance) than those fed low doses, where more TGF-β and less IL-4 are produced." (PMID 22203855, 2012). "It is well known that Th2 cells orchestrate allergy-induced asthmatic inflammatory responses, and the main immune abnormalities are caused by Th2 cytokines, such as IL-4 and IL-5, which induce eosinophil infiltration and airway hyperresponsiveness." (PMID 22545078, 2012). "In particular, IL-4 and IL-13 are involved in the isotype switch from IgM to IgE, the antibody responsible for classic allergy and implicated in the pathophysiology of allergic asthma." (PMID 20616938, 2010). "Additionally, rs2243250 (IL-4) CC homozygotes with vitamin D deficiency exhibited elevated allergy risk (adjusted OR = 4.13, 95% CI: 1.48–11.57, p = 0.007)." (PMID 40927566, 2025). "However, rs2243250 (IL-4) exhibited a trend toward reduced allergy risk in the dominant model (TT vs. TC+CC: adjusted OR = 0.59, 95% CI: 0.34–1.03, p = 0.062)." (PMID 40927566, 2025). "Some studies suggest that insufficient sleep can alter levels of inflammatory cytokines such as interleukin (IL)-1β, IL-4, IL-6, and IL-10, which may promote allergic reactions and elevate the risk of developing AR." (PMID 40283018, 2025). "One of the advantages of the approach we used was to highlight the SNP clusters identified by the market basket analysis also the presence of genotypes of the SNPs IL-4 rs2243250 and IL-4R rs1801275 associated with allergy, respectively, in five and two of the clusters identified." (PMID 39202464, 2024). "In particular, IL-4 rs2243250, IL-4R rs1801275, and IL-13 rs1800925 variants, affecting expression and/or functionality of the gene products were considered markers of predisposition to allergy." (PMID 39202464, 2024). "IL-4 further induces the differentiation of Th2 cells, which leads to the release of Th2-associated cytokines (IL-4/5/13), inhibits the proliferation of Th1 cells, and enhances the degranulation of mast cells, thereby exacerbating allergic reactions." (PMID 38812518, 2024). "Suppression of the TSLP signaling and lack of basophil-derived IL-4 synthesis was found to inhibit food-induced allergic reaction in the intestine confirming the crucial role of TSLP-basophil-IL-4 axis in epicutaneous sensitization and associated pathogenesis of IgE-mediated food allergy." (PMID 36904070, 2023).
Allergy (continued). "By contrast, clinical allergy is caused by dysregulated type 2 immunity, which is characterized by expansion of T helper 2 (Th2) cells and eosinophils, as well as overproduction of the associated cytokines IL-4, IL-5, IL-9, and IL-13." (PMID 35281022, 2022). "Obviously, genetic factors like special variants of the IL-4, IL-4R, and IL-13 genes may have a prominent role in development of allergy; therefore, their contribution should be carefully noticed." (PMID 35307016, 2022). "As high IL-4 and IgE levels are hallmarks of several disorders associated with allergic disease, the serological and histological analysis markers improved by trifuhalol A intake provide a direct demonstration of the anti-allergic inflammatory effect of trifuhalol A in an animal model of AD." (PMID 36077570, 2022). "In this study, Ch. pneumonia strain was propagated and cultured in HEp-2 cells according to standard protocol and infant C57BL/6 mice around 3-4 weeks old were infected to study the role of IL-4 in respiratory infection and allergy caused by early life Chlamydia infection." (PMID 34226412, 2021). "AR with neuroinflammatory markers may trigger allergies caused by IL-4, IL-5 and IL-6 and, thus, affect psychopathology, such as depression, that may be associated with increased inflammatory markers." (PMID 34689833, 2021). "Therefore, the present study is an attempt to study the role of IL-4 in respiratory infection and allergy caused by early-life Ch. pneumoniae infection using a mouse model." (PMID 34226412, 2021). "In addition, IL-4 is mainly responsible for the production of immunoglobulin (Ig) E, which is strongly associated with allergies, by eliciting Ig class switching in response to stimuli." (PMID 33406620, 2021). "Since a cytokine imbalance in the IFNγ/IL4 ratio from iNKT cells is associated with the pathogenesis of allergic diseases, we determined whether repeated α-GalCer activation alters the cytokine profiles of activated iNKT cells from Vα14Tg NC mice." (PMID 34829848, 2021). "According to these data, we can infer that children conceived by fresh embryo transfer via ART tended to have elevated plasma IL-4 levels and might face a higher risk of allergic diseases." (PMID 34836513, 2021). "Allergic diseases are closely associated with dysregulated T helper 2 cells (Th2 cells) immune responses to allergens, which are characterized by elevated secretion of Th2-specific cytokines including interleukin 4 (IL-4), IL-5, and IL-13." (PMID 33919400, 2021). "Moreover, associations of the IL-4 polymorphisms with the recurrent abortion, pregnancy specific-disorder of pre-eclampsia, allergic diseases, and serum immunoglobulin E (IgE) levels have been reported in humans and mice." (PMID 33920608, 2021). "Contrary to a pro-Th2 effect of c-Maf on the immune response, increased Th2 lung pathology, associated with higher numbers of eosinophils in bronchoalveolar lavage fluids, was observed in the HDM allergy model despite a decreased expression of Il4 in T-cell specific c-Maf deficient mice." (PMID 32117317, 2020). "IL-4 induces the B cell class switching to IgE and is associated with allergy." (PMID 32334611, 2020). "In this review, it is argued that allergy represents an environmental risk factor for autism spectrum disorders, which involves a cascade of events including the Th2-cytokines IL4 and IL13, an M2A polarization of microglia, the release of growth factors, and the inhibition of autophagy in neurons." (PMID 29232822, 2017). "In addition to proteins, the polysaccharide chitin is also known to induce allergy by causing accumulation of interleukin-4 (IL-4)-expressing innate immune cells." (PMID 27247234, 2016). "Using prior knowledge and examining correlations among 12 serum proteins, we have identified an interaction between IL4 and sIL4RA and glioma that is present long before tumor diagnosis and may therefore represent a route by which allergy reduces glioma risk." (PMID 26352148, 2015).